RREB1 (ras responsive element binding protein 1)
Description:
Transcription factor that binds specifically to the RAS-responsive elements (RRE) of gene promoters. Represses the angiotensinogen gene. Negatively regulates the transcriptional activity of AR. Potentiates the transcriptional activity of NEUROD1. Promotes brown adipocyte differentiation (By similarity). May be involved in Ras/Raf-mediated cell differentiation by enhancing calcitonin expression.
Synonyms: RREB-1; Zep-1; FINB; HNT; LZ321
Tractability: PROTAC: UniProt records ubiquitination sites on it; ubiquitination databases record sites on it; its protein half-life has been measured.
Gene: Protein-coding gene on chromosome 6 (7,107,418 to 7,251,982, forward strand). Ensembl gene ENSG00000124782.
Subcellular location: Nucleus speckle
Subcellular location (Human Protein Atlas): Nuclear speckles; Nucleoli fibrillar center
Gene Ontology:
Molecular function: DNA-binding transcription activator activity, RNA polymerase II-specific; RNA polymerase II cis-regulatory region sequence-specific DNA binding; RNA polymerase II transcription regulatory region sequence-specific DNA binding; DNA-binding transcription factor activity
Biological process: negative regulation of transcription by RNA polymerase II; positive regulation of epithelial cell migration; positive regulation of lamellipodium morphogenesis; positive regulation of mammary gland epithelial cell proliferation; positive regulation of substrate adhesion-dependent cell spreading; positive regulation of transcription by RNA polymerase II; positive regulation of wound healing, spreading of epidermal cells; positive regulation of brown fat cell differentiation; positive regulation of DNA-templated transcription; regulation of DNA-templated transcription; regulation of transcription by RNA polymerase II; transcription by RNA polymerase II; positive regulation of developmental process
Cellular component: extracellular exosome; nuclear speck; cytoplasm; nuclear body; nucleus
Genetic constraint (gnomAD): Loss-of-function variants: 27 observed, 101.66 expected, observed/expected ratio (o/e) 0.27, 90% interval 0.19 to 0.37. The synonymous counts are far from expectation, so gnomAD's model fits this gene poorly and the ratio says little. Missense variants: 2,549 observed, 2,295.3 expected, observed/expected ratio (o/e) 1.11, 90% interval 1.07 to 1.15. Synonymous variants: 1,284 observed, 1,009.2 expected, observed/expected ratio (o/e) 1.27, 90% interval 1.21 to 1.33.
Homologues: Orthologues: chimpanzee RREB1 (99% identical), macaque RREB1 (97% identical), dog RREB1 (83% identical), guinea pig RREB1 (82% identical), mouse Rreb1 (81% identical), rat Rreb1 (80% identical), rabbit RREB1 (71% identical), tropical clawed frog rreb1 (53% identical), zebrafish rreb1a (44% identical), zebrafish rreb1b (40% identical), Drosophila melanogaster peb (21% identical). Paralogues in human: HIVEP1 (15% identical), HIVEP2 (14% identical), HIVEP3 (14% identical), ZNF831 (10% identical), SALL1 (8% identical), SALL3 (8% identical), ZNF536 (7% identical), BCL11B (6% identical), ZNF516 (6% identical), BCL11A (6% identical), SALL4 (6% identical), ZNF217 (5% identical), and 2 more.
Diseases named in the same sentence as RREB1 in open-access papers:
RREB1 is named in the same sentence as 71 diseases in open-access papers, as found by Europe PMC text mining. Sharing a sentence is not in itself a finding about the gene and the disease. The quoted sentences say what the papers report.
pancreatic cancer (18 papers, 2012 to 2025). "These putative novel missense mutational cancer genes include RREB1 (Ras Responsive Element Binding Protein 1, in hepatocellular carcinoma), which is a gene previously found to be significantly mutated in pancreatic carcinoma and dysregulated in cancer." (PMID 34313788, 2021). "Loss of miR-145 expression is also observed frequently inKRAS-mutated pancreatic cancer, and thedownregulation of miR-145 requires Ras-responsive element-binding protein (RREB1) torepress its promoter." (PMID 25106061, 2014). "Another study found that the downregulation of zinc transporter 3 (ZIP3) and RREB1 coincided with zinc loss during the early progression of pancreatic cancer and may help malignant cells eliminate the cytotoxic effects of zinc." (PMID 37829346, 2023). "Continuously activated KRAS signaling in pancreatic cancer cells activates RREB1, which promote the binding of SMAD2/3 to the cis-regulatory regions of target genes." (PMID 39913299, 2025). "RREB1 is also involved in the KRAS-induced transformation of pancreatic cancer via repressing the tumor suppressor miR-143/145." (PMID 32210733, 2020). "On the other hand, the low level of zinc is crucial to survival of pancreatic cancer cells, and RREB1 inhibits the proliferation of pancreatic cancer through upregulating the zinc level." (PMID 32210733, 2020). "The functional role of RREB1 in pancreatic cancer is still controversial due to multiple mechanisms involvement." (PMID 32210733, 2020). "Though RREB1 exerts an oncogene or repressor gene in several cancers, the role of RREB1 in pancreatic cancer is still controversial." (PMID 32210733, 2020). "Studies also propose that RREB1 is an oncogene to promote the phenotype transformation in pancreatic cancer." (PMID 32210733, 2020). "Relieving the negative regulation of RREB1 on ARHGEF2 contributes to the migratory behavior of pancreatic cancer cells." (PMID 32210733, 2020). "A previous study reported that the RREB1/ZIP3/ZINC complex arises in early-stage human pancreatic cancers and suppresses the development of malignant cells." (PMID 32266133, 2020). "Targeting RREB1 expression with RNA interfering in vitro and in vivo will reduce tumor cell growth of pancreatic cancer." (PMID 32210733, 2020). "Even though there is less literature focusing on the relationship between RCC and RREB-1, some mechanistic studies have suggested that the RREB-1 has a major role in tumor suppression of pancreatic cancer, bladder cancer, prostate cancer." (PMID 31346320, 2019). "RREB1 expression has also been shown to decrease during PanIN development in pancreatic cancer consistent with our results observed in tumor xenografts." (PMID 27835861, 2017). "Furthermore, Ras-responsive element binding protein 1 (RREB1) represses miR-143/miR-145 promoter activity, which indicates that repression is an early event in pancreatic cancer initiation and progression." (PMID 24040120, 2013). "With these data, we speculate that DCLK1 plays a role in post-transcriptional regulation of miR-143/145 cluster and thereby downregulates KRAS and RREB1 in pancreatic tumor xenografts." (PMID 24040120, 2013). "As a transcription factor, RREB1 was identified to upregulate lncRNA AGAP2-AS1 and promote the progression of pancreatic cancer." (PMID 37596700, 2023). "RREB1 has been identified a negative regulator of RHO guanine exchange factor ARHGEF2 that is essential for the growth and survival of pancreatic cancer." (PMID 32210733, 2020). "Subsequent studies validated that restoration of miR-143 34 or miR-145 35 retard the transformation of pancreatic cancer at least partly through downregulation of KRAS and RREB1." (PMID 32210733, 2020). "Meanwhile, the RREB1 transcription factor and ZIP3 zinc uptake transporter were downregulated, leading to the progression of pancreatic cancer." (PMID 32210733, 2020). "RREB1 is also overexpressed in pancreatic cancer compared with normal tissue." (PMID 32210733, 2020).
pancreatic cancer (continued). "Similarly, in Kirsten rat sarcoma (RAS) mutant pancreatic cancers, the RAS oncogene binds, through its RAS-responsive element-binding (RREB1), the promoter of the miR-143/145 family, which normally act as repressors of the same RAS and RREB1 transcription factors." (PMID 35267528, 2022).
melanoma (16 papers, 2013 to 2025). A malignant, usually aggressive tumor composed of atypical, neoplastic melanocytes. "At present, the clinical application of RREB1 is mainly used as a molecular diagnostic marker for melanoma." (PMID 32210733, 2020). "Remarkably, from TFs present in our DEPs list, we can emphasize the downregulation of the Ras-responsive element binding protein 1 (RREB1), a reliable marker for diagnosis and prognosis prediction in melanoma." (PMID 38928466, 2024). "In melanomas this probe set panel identified interchromsomal rearrangement in chromosome 6 with gains in 6p25 (RREB1) and loses in 6q23 (MYB), as well as common gains in 11q13 (CCND1)." (PMID 39741925, 2024). "The frequent amplification of RREB1 in melanoma suggests its important role in melanoma tumorigenesis, and it is used as a good marker for tumor diagnosis, prognosis prediction, and patient management." (PMID 38928466, 2024). "The findings and insights generated from this study support the importance of RREB1 and its role in melanoma tumorigenesis by inhibiting the action of tumor suppressor genes." (PMID 38928466, 2024). "As a result, a number of studies using conventional melanoma FISH probes (RREB1, CCND1, MYB, CEP6) have been performed in recent years." (PMID 38031947, 2023). "We analyzed 39 cases of atypical Spitz tumor (AST), 10 cases of melanomas with spitzoid features for clinicopathological data and chromosomal alterations, targeting RREB-1 (6p25), CCND1 (11q13), MYB (6q23), together with 9p21 (CDKN2A), using FISH methodology." (PMID 38031947, 2023). "Frequent amplification of RREB1 in melanoma suggests us the important role of RREB1 in the tumorigenesis of melanoma." (PMID 32210733, 2020). "RREB1 (Ras-responsive element binding protein 1) participates in Ras signaling and cancer progression in bladder cancer prostate cancer, and melanoma." (PMID 23966867, 2013). "In conclusion, 3e seems to deregulate pathways involved in melanoma pathogenesis, and RREB1 down-regulation could be one of the players in such an effect." (PMID 38928466, 2024). "It is of note that the role of RREB1 in melanoma diagnosis is particularly important." (PMID 32210733, 2020). "We also review the current clinical application of RREB1 as a biomarker for melanoma detection." (PMID 32210733, 2020). "Although we cannot exclude a structural interaction between compound 3e and RREB1, our results suggest its regulation at the expression level, which may serve as a potential explanation for the influence of imidazo–pyrazole 3e compound on melanoma cells." (PMID 38928466, 2024). "In this light, RREB1 downregulation could be considered a molecular target in melanoma." (PMID 38928466, 2024). "Therefore, RREB1 may be a crucial driver-gene to initiate the melanoma by inhibiting tumor suppressors." (PMID 32210733, 2020). "In contrast, PEM typically bear no mutations in TERT promoter or unbalanced copy number changes in known oncogenes (RREB1, MYB1, CCND1, CKND2A) and presence of these molecular changes should raise the suspicion for melanomas." (PMID 34943205, 2021). "Four-color FISH for CCDN1, MYB, RREB1 and CEP6 has been developed and suggested as a tool for that purpose, screening for common chromosomal changes in melanomas." (PMID 34943205, 2021). "In this study, we aimed to evaluate the diagnostic value of four-color fluorescence in-situ hybridization (FISH) probes specific to the RREB1,CCND1,and MYB genes, and centromere of chromosome 6, in distinguishing DN and melanoma." (PMID 32393283, 2020). "Array CGH results were further confirmed by four colour FISH experiments specific for 11q13 (specific for CCND1 gene), 6p25 (specific for RREB1 gene), 6q23 (specific for MYB gene) and centromere 6 on 27 primary melanomas." (PMID 24832207, 2014). "Notably, we highlight the down-regulation of the Ras-responsive element binding protein 1 (RREB1), a member of the zinc finger transcription factors family involved in the tumorigenesis of melanoma." (PMID 38928466, 2024).
melanoma (continued). "Fluorescence in-situ hybridization (FISH) utilizing probes for genes RREB1 (6p25), cMYC (8q24), CDKN2A (p16)/CEN9, and CCND1 (11q13) has been shown to be sensitive and specific for differentiating Spitz nevi from spitzoid appearing melanoma." (PMID 37877026, 2023). "Additionally, imidazo-pyrazole derivative Ib showed low micromolar IC50 values against the skin melanoma SKMEL-28 cell line and proteomics studies evidenced its ability to downregulate Ras-responsive element binding protein 1 (RREB1), a crucial molecular target in SKMEL-28 melanoma cells." (PMID 40650091, 2025).
prostate carcinoma (8 papers, 2013 to 2026). A carcinoma that arises from epithelial cells of the prostate gland. "RREB1 promotes prostate cancer by activating the transcription of SNHG4, which promotes DNA damage repair, the cell cycle, and resistance to the androgen-receptor antagonist enzalutamide." (PMID 41516419, 2026). "Our study uncovered a novel molecular mechanism of lncRNA SNHG4 in driving prostate cancer progression and enzalutamide resistance, revealing the critical roles and therapeutic potential of RREB1, SNHG4, RRM2 and let-7 miRNAs in anticancer therapy." (PMID 37596700, 2023). "Our study uncovered a novel molecular mechanism of lncRNA SNHG4 in driving prostate cancer progression and enzalutamide resistance, revealing the critical roles and therapeutic potential of RREB1, SNHG4 and let-7 miRNAs in anticancer therapy." (PMID 37596700, 2023). "Although there are few reports about RREB1 in prostate cancer, RREB1 is indeed involved in the development of prostate cancer." (PMID 32210733, 2020). "The overexpression of Ras-responsive element binding protein 1 (RREB1) is involved in ZIP1 downregulation in prostate cancer." (PMID 32944394, 2020). "Overexpressed RREB1 decreases the zinc level to provide a microenvironment for the growth of prostate cancer cells." (PMID 32210733, 2020). "An imbalance of RREB1 function plays a role in the development of various cancers and other diseases including prostate cancer 9, colorectal cancer 5,10, urologic cancer 11, type 2 diabetes 12, leukemia 13 and intervertebral disc degeneration." (PMID 32210733, 2020). "Little is known about the functions of RREB1 in prostate cancer." (PMID 37596700, 2023). "However, the functions and mechanisms of RREB1 in regulating the tumorigenesis of prostate cancer need to be further investigated." (PMID 37596700, 2023). "RREB1 is also involved in the regulation of prostate cancer development by inhibiting hZIP1." (PMID 32210733, 2020). "Additionally, RREB1 has been reported to downregulate the zinc level in prostate cancer through inhibiting the hZIP1 zinc transporter." (PMID 32210733, 2020). "Expression of RREB1 is significantly increased in prostate cancer tissue." (PMID 32210733, 2020). "The RREB1/SNHG4/let-7a regulatory loop may enhance the aggressiveness of prostate cancer." (PMID 37596700, 2023). "Therefore, we hypothesized that RREB1 transcriptionally regulates SNHG4 expression in prostate cancer." (PMID 37596700, 2023). "Certain study revealed that the upregulation of Ras-responsive element binding protein 1 (RREB1) led to the downregulation of zinc transporter 1 (ZIP1) and influenced zinc reduction in prostate cancer." (PMID 37829346, 2023). "RREB1 is a downstream effector of the Ras-Raf-MEK-ERK pathway and is upregulated during prostate cancer progression." (PMID 32944394, 2020). "Upregulation of RREB1 in the early development of malignancy leads to ZIP1 downregulation and a subsequent zinc decrease in prostate cancer." (PMID 32944394, 2020). "In prostate cancer, oncogenic KRAS signalling led to suppression of miR-143/145 cluster by activating Ras-responsive element-binding protein 1 (REBB1)." (PMID 29360852, 2018). "However, RREB1 plays a negative role in prostate cancer by binding to the ACCCAAACTTACCC sequence of hZIP1." (PMID 32210733, 2020).
diabetes (7 papers, 2019 to 2025). "As the RREB1 locus is associated with altered diabetes risk and beta cell-related traits in humans, we first investigated the impact of loss of RREB1 at an organismal level." (PMID 36633628, 2023). "Among the differentially methylated CpG sites, epigenetic markers were found at human hepatocyte nuclear factors 4α (HNF4A) and at the ras responsive element binding protein 1 (RREB1), associated with diabetes and obesity." (PMID 32933073, 2020). "For example, among the candidate genes were known susceptibility loci for diabetes (PTPN22, CEP68, RREB1, TCF7L2), coronary artery disease (PSRC1, UNC5C, LPLA), depression (MAD1L1, YLPM1) and insomnia (NMT1)." (PMID 38541061, 2024). "They identified 12 differentially methylated CpG sites in the GDM-exposed group, two of which have been linked to monogenic diabetes (hepatocyte nuclear factor 4 alpha, HNF4A) and obesity (Ras responsive element binding protein 1, RREB1)." (PMID 34968300, 2021). "Therefore, RREB1 may also be one of the pathogenic genes of diabetes." (PMID 32210733, 2020). "EGR1 and EGR2 play a key role in insulin signaling and lipid metabolism and have been involved in adipocyte differentiation programs, and RREB1 has been shown as novel candidate gene for diabetes affecting insulin sensitivity, beta-cell function and adipogenesis." (PMID 40646607, 2025). "The contradictory finding that carriers of the RREB1 protective allele have lower insulin secretion levels but are protected from type 2 diabetes hints at potential additional functions of RREB1 in other diabetes-relevant tissues (e.g. insulin-responsive tissues)." (PMID 36633628, 2023). "However, little is known about the function of the zinc finger transcription factor Ras-responsive element binding protein 1 (RREB1) in glucose homeostasis or how changes in its expression and/or function influence diabetes risk." (PMID 36633628, 2023). "RREB1 also plays an important role in the development of metabolic diseases, such as diabetes." (PMID 32210733, 2020). "These evidences suggest that RREB1 plays an important role in diabetes, but the specific mechanism remains unclear." (PMID 32210733, 2020). "CDKAL1, RREB1, and PPARG were not significant in either arm of the diabetes stratified analysis, while RAI1 and SLC9B2 were significant in the non-diabetes group." (PMID 31451708, 2019).